CLP1 (cleavage factor polyribonucleotide kinase subunit 1)
Description:
Polynucleotide kinase that can phosphorylate the 5'-hydroxyl groups of double-stranded RNA (dsRNA), single-stranded RNA (ssRNA), double-stranded DNA (dsDNA) and double-stranded DNA:RNA hybrids. dsRNA is phosphorylated more efficiently than dsDNA, and the RNA component of a DNA:RNA hybrid is phosphorylated more efficiently than the DNA component. Plays a key role in both tRNA splicing and mRNA 3'-end formation. Component of the tRNA splicing endonuclease complex: phosphorylates the 5'-terminus of the tRNA 3'-exon during tRNA splicing; this phosphorylation event is a prerequisite for the subsequent ligation of the two exon halves and the production of a mature tRNA. Its role in tRNA splicing and maturation is required for cerebellar development. Component of the pre-mRNA cleavage complex II (CF-II), which seems to be required for mRNA 3'-end formation. Also phosphorylates the 5'-terminus of exogenously introduced short interfering RNAs (siRNAs), which is a necessary prerequisite for their incorporation into the RNA-induced silencing complex (RISC). However, endogenous siRNAs and microRNAs (miRNAs) that are produced by the cleavage of dsRNA precursors by DICER1 already contain a 5'-phosphate group, so this protein may be dispensible for normal RNA-mediated gene silencing.
Synonyms: HEAB; hClp1
Tractability: PROTAC: ubiquitination databases record sites on it; its protein half-life has been measured.
Gene: Protein-coding gene on chromosome 11 (57,648,188 to 57,661,865, forward strand). Ensembl gene ENSG00000172409.
Subcellular location: Nucleus
Subcellular location (Human Protein Atlas): Nucleoplasm; Cytosol
Pathways (Reactome):
Metabolism of RNA: Processing of Intronless Pre-mRNAs; mRNA 3'-end processing; mRNA Polyadenylation; tRNA processing in the nucleus
Disease: Dengue Virus-Host Interactions
Gene expression (Transcription): RNA Polymerase II Transcription Termination
Gene Ontology:
Molecular function: ATP-dependent polydeoxyribonucleotide 5'-hydroxyl-kinase activity; ATP-dependent polyribonucleotide 5'-hydroxyl-kinase activity; protein binding; ATP binding; polynucleotide 5'-hydroxyl-kinase activity; ATP-dependent polynucleotide 5'-hydroxyl-kinase activity
Biological process: cerebellar cortex development; regulation of mRNA 3'-end processing; RISC complex assembly; tRNA splicing, via endonucleolytic cleavage and ligation; tRNA-type intron splice site recognition and cleavage; mRNA 3'-end processing; RNA processing
Cellular component: mRNA cleavage factor complex; nucleoplasm; nucleus; tRNA-intron endonuclease complex
Genetic constraint (gnomAD): Loss-of-function variants: 18 observed, 31.18 expected, observed/expected ratio (o/e) 0.58, 90% interval 0.4 to 0.86. The synonymous counts are far from expectation, so gnomAD's model fits this gene poorly and the ratio says little. Missense variants: 357 observed, 572.5 expected, observed/expected ratio (o/e) 0.62, 90% interval 0.57 to 0.68. Synonymous variants: 162 observed, 218.39 expected, observed/expected ratio (o/e) 0.74, 90% interval 0.65 to 0.85.
Homologues: Orthologues: chimpanzee CLP1 (100% identical), macaque CLP1 (100% identical), dog CLP1 (99% identical), pig CLP1 (99% identical), rabbit CLP1 (99% identical), mouse Clp1 (99% identical), rat Clp1 (99% identical), guinea pig CLP1 (97% identical), zebrafish clp1 (79% identical), tropical clawed frog clp1 (77% identical), Drosophila melanogaster cbc (55% identical), Caenorhabditis elegans clpf-1 (48% identical). Paralogues in human: NOL9 (21% identical).
Diseases named in the same sentence as CLP1 in open-access papers:
CLP1 is named in the same sentence as 42 diseases in open-access papers, as found by Europe PMC text mining. Sharing a sentence is not in itself a finding about the gene and the disease. The quoted sentences say what the papers report.
pontocerebellar hypoplasia (6 papers, 2019 to 2025). Pontocerebellar hypoplasias (PCH) are a rare heterogeneous group of diseases characterized by hypoplasia and atrophy and/or early neurodegeneration of the cerebellum and pons. "Mutations in the human TSEN complex and its regulatory factor Clp1 are linked to a range of neurodegenerative diseases, including various forms of pontocerebellar hypoplasia (PCH) and intellectual disability." (PMID 37770519, 2023). "Mutations in TSEN/CLP1 occur in patients with pontocerebellar hypoplasia (PCH), however, their role in the disease is unclear." (PMID 34584079, 2021). "A mutation in the CLP1 gene, which encodes the RNA kinases spliced by tRNA, has been found in patients with pontocerebellar hypoplasia (PCH)." (PMID 34341710, 2021). "Interestingly, mutations in CLP1 or TSEN genes cause neurological diseases in humans that are collectively termed Pontocerebellar Hypoplasia (PCH)." (PMID 35132432, 2022).
microcephaly (5 papers, 2017 to 2025). A congenital or acquired developmental disorder in which the circumference of the head is smaller than normal for the person's age and sex. "The patients carrying the CLP1 mutation and CLP1 kinase-dead mice exhibit microcephaly and deficits in motor and sensory function." (PMID 41415912, 2025). "Mutations in all four subunits of the TSEN complex and in CLP1 have been reported as the cause of pathology, which displays a variety of symptoms including microcephaly, loss of motor development and intellectual disabilities." (PMID 40745156, 2025). "For instance, CLP1, which encodes an RNA kinase responsible for tRNA splicing required for tRNA maturation, causes microcephaly in humans, mice and zebrafish and peripheral neuropathy in humans." (PMID 30755616, 2019).
pontocerebellar hypoplasia type 10 (4 papers, 2021 to 2025). Any non-syndromic pontocerebellar hypoplasia in which the cause of the disease is a mutation in the CLP1 gene. "Rare genetic mutations in CLP1 are associated with pontocerebellar hypoplasia type 10, a very rare autosomal recessive neurodegenerative disease characterized by brain atrophy and delayed myelination resulting in intellectual disability." (PMID 40360802, 2025). "Homozygous mutation of the RNA kinase CLP1 (cleavage factor polyribonucleotide kinase subunit 1) causes pontocerebellar hypoplasia type 10 (PCH10), a pediatric neurodegenerative disease." (PMID 34548404, 2021). "Mutation of CLP1 causes pontocerebellar hypoplasia type 10 (PCH10), a neurodegenerative disorder associated with intellectual and motor disability." (PMID 34548404, 2021). "Homozygosity for the R140H (arginine to histidine) missense mutation in the RNA kinase CLP1 (cleavage factor polyribonucleotide kinase subunit 1) causes the pediatric disorder pontocerebellar hypoplasia type 10 (PCH10)." (PMID 34548404, 2021).
cyst (2 papers, 2024 to 2025). A sac-like closed membranous structure that may be empty or contain fluid or amorphous material. "The thickening caused by CLP1 deletion is also associated with a reduction in cyst burden over time in vivo." (PMID 40071939, 2025). "On the other hand, during the bradyzoite stage, Myc-tagged CLP1 was only found around the apical complex or surface of parasite, but after reactivation stimulation, it also relocated to reside near the cyst wall." (PMID 38828265, 2024). "And also, these results suggested that CLP1 has some interaction with the cyst wall during reactivation." (PMID 38828265, 2024). "Using a chitinase-like protein (CLP1) knockout, they show that in the absence of CLP1, the cyst wall becomes thicker, and the protein composition alters with several proteins over or underrepresented following knockout of CLP1." (PMID 40071939, 2025).
type 2 diabetes (2 papers, 2019 to 2021). "The final mechanism is slowing gastric emptying, inhibiting the inappropriate release of postprandial glucagon, and possibly inhibiting the appetite control center of the brain CLP-1 analogs are currently used for patients with type 2 diabetes (T2DM), as well as for patients with obesity." (PMID 34335269, 2021).
ataxia telangiectasia (1 paper, 2021). Ataxia-telangiectasia is the association of severe combined immunodeficiency (affecting mainly the humoral immune response) with progressive cerebellar ataxia. "Nevertheless, ionizing radiation activates miR-34 by phosphorylation dependent of ATM (ataxia telangiectasia) and the RNA 5’kinase Clp1 (cleavage factor polyribonucleotide kinase subunit 1)." (PMID 34803905, 2021).
cardiac hypertrophy (1 paper, 2009). "Briefly, ectopic activation of P-TEFb either by ablation of cardiac lineage protein 1 (Clp-1), the mouse homologue of Hexim1, or overexpression of CycT1 in adult heart led to fetal lethality or heart growth due to cardiac hypertrophy, respectively." (PMID 19723344, 2009). "Genetic ablation of Clp-1, the mouse homologue of human Hexim1, resulted in embryonic death at E16.5 due to cardiac hypertrophy." (PMID 19723344, 2009).
Cerebellar atrophy (1 paper, 2024). Cerebellar atrophy is defined as a cerebellum with initially normal structures, in a posterior fossa with normal size, which displays enlarged fissures (interfolial spaces) in comparison to the foliae secondary to loss of tissue. "The PCH10 case (case 9), harboring the c.784C > G variant in the CLP1 gene, displayed an absence of abnormality in MRI findings, diverging from previous cases characterized by cortical and cerebellar atrophy." (PMID 38347586, 2024).
cervical cancer (1 paper, 2025). A primary or metastatic malignant neoplasm involving the cervix. "μ-Calpain cleaves pRB in cervical cancer cells, so we investigated CLP-1/CAPN, the most similar C. elegans homolog of μ-Calpain." (PMID 40199585, 2025).
diabetic retinopathy (1 paper, 2017). "It is interesting, however, that mutations in COLEC12, collectin subfamily member 12 (CLP1), have been associated with profound alterations in brain development and diabetic retinopathy." (PMID 29190776, 2017).
Duchenne muscular dystrophy (1 paper, 2012). Duchenne muscular dystrophy (DMD) is a neuromuscular disease characterized by rapidly progressive muscle weakness and wasting due to degeneration of skeletal, smooth and cardiac muscle. "We find that CLP-1 contributes to the muscle degeneration observed in a model of Duchenne muscular dystrophy." (PMID 22479198, 2012).
graft versus host disease (1 paper, 2022). An immune system disorder that occurs after allogeneic hematopoietic stem cell transplant and is a reaction of donor immune cells against host tissues. "The KEGG-GSEA analysis results suggest that CLP1 is also involved in arginine and proline metabolism, systemic lupus erythematosus, graft-versus-host disease, and other disease processes, which also confirms the role of CLP1 in autoimmune system diseases." (PMID 35721104, 2022).
muscular dystrophy (1 paper, 2012). Muscular dystrophy (MD) refers to a group of more than 30 genetic diseases characterized by progressive weakness and degeneration of the skeletal muscles that control movement. "Given the association between calpain activity and degenerative pathologies, we have investigated factors that influence the activity of clp-1 in a C. elegans model of muscular dystrophy and reveal the importance of both sustained calpain expression and intracellular Ca2+ levels ([Ca2+]i)." (PMID 22479198, 2012). "We find that the muscle degeneration observed in a C. elegans model of dystrophin-based muscular dystrophy can be suppressed by clp-1 inactivation and that nemadipine-A inhibition of the EGL-19 calcium channel reveals that Ca2+ dysfunction underlies the C. elegans MyoD model of myopathy." (PMID 22479198, 2012).
Neurodegeneration (1 paper, 2025). Progressive loss of neural cells and tissue. "For example, a pathogenic variant of the CPA gene CLP1 was found to alter mRNA processing patterns in neurodegeneration disease models." (PMID 41463412, 2025).
pulmonary diseases (1 paper, 2021). "For example, CLP1 is linked to cardiac muscle hypertrophy, YPEL4 has a role in pulmonary diseases, P2RX3 and ENSGALG00000007381 are involved in blood coagulation (Reactome; Uniprot), and SLC43A3 plays a possible important role in the repair and growth of the lung tissue under oxidative stress." (PMID 34021753, 2021).
infection (5 papers, 2013 to 2025). The state of being infected such as from the introduction of a foreign agent such as serum, vaccine, antigenic substance or organism. "Splicing is induced during infection, resulting in the expression of a Cib1 variant containing a functionally important Clp1 interaction domain." (PMID 24146612, 2013). "We confirmed that cells remained viable after knockdown of Tsen2 and Clp1 followed by MHV68-MR infection." (PMID 40444975, 2025). "Biz1, Clp1, and Kpp6 were significantly upregulated only after 9 days of infection in the UeMsb2 deletion strains, with expression levels markedly lower than those in the wild-type and complementation strains at the same time point." (PMID 39728314, 2024). "This study revealed that the deletion of UeMsb2 significantly reduced the expression of b signaling pathway genes, including Prf1, Hdp1, Rbf1, Biz1, Clp1, and Kpp6, during hyphal growth and infection in U. esculenta." (PMID 39728314, 2024). "Here, we report a Cti6-like protein, Clp1, that is involved in fungal development and infection of plants through controlling autophagy homeostasis in the cytoplasm and gene transcription in the nucleus in M. oryzae." (PMID 36036638, 2022). "Progression toward infection is regulated by several bE/bW-induced factors, including Clp1 and Cib1." (PMID 24146612, 2013). "They showed that these two plant miRNAs were present inside the fungal cells and induced upon infection, while their putative fungal target genes, Ca2+-dependent cysteine protease (Clp-1) and isotrichodermin C-15 hydroxylase (HiC-15), were downregulated in fungal hyphae." (PMID 38875250, 2024).
tumor (5 papers, 2017 to 2025). "We discovered that DAF-18/PTEN protects another important tumor suppressor, LIN-35/Rb, from being cleaved by CLP-1/CAPN, permitting LIN-35/Rb to promote starvation resistance." (PMID 40199585, 2025). "Scatter plots revealed that CLP1, CPSF2, and NUDT21 expressed significantly higher in tumor tissues than in normal gastric tissues, which was completely consistent with the results of the TCGA database." (PMID 36874129, 2023).
cancer (4 papers, 2018 to 2025). A tumor composed of atypical neoplastic, often pleomorphic cells that invade other tissues. "A second set consisted of an additional 15 cancer-related genes (Nf1, Mki67, Mllt4, Fgfr2, Ctnnb1, Fat1, Clp1, Fat4, Arid1a, Nat1, Nat2, Setd2, Impg1, Nbas and Npat)." (PMID 29925311, 2018).
infectious disease (2 papers, 2010 to 2018). A disorder directly resulting from the presence and activity of a microbial, viral, or parasitic agent in humans. "We observed that top functions these genes involved are RNA post-Transcriptional Modification (CLP1 TSEN2 and TSEN54) and infectious disease and inflammatory disease (NR3C1, PPP3CC, and PPP3R1)." (PMID 21172007, 2010).
myopathy (1 paper, 2012). A disease of the muscle in which the muscle fibers do not function properly. "Nonetheless, removal of clp-1 substantially suppressed the muscle degeneration associated with C. elegans dys-1; hlh-1(cc561ts) DMD, which is based on a mouse model of myopathy involving the combined mutation of MyoD and dystrophin." (PMID 22479198, 2012).
CLP1 also shares sentences with these, for which no sentence is quoted: neurodegenerative disease (3 papers); neurological diseases (2); atrial septal defect (1); autoimmune disease (1); bladder cancer (1); Brain atrophy (1); cardiovascular disorder (1); developmental delay (1); Hypertonia (1); Hypotonia (1); Intellectual disability (1); morbid obesity (1); orofacial cleft (1); Paralysis (1); Patent ductus arteriosus (1); Patent foramen ovale (1); peripheral neuropathy (1); psychiatric disorder (1); rheumatoid arthritis (1); schizophrenia (1); systemic lupus erythematosus (1); type 2 diabetes mellitus (1).